EZH2 (enhancer of zeste 2 polycomb repressive complex 2 subunit)
Diseases named in the same sentence as EZH2 in open-access papers (continued):
Sharing a sentence is not in itself a finding about the gene and the disease.
cervical carcinoma (56 papers, 2006 to 2025). A carcinoma arising from either the exocervical squamous epithelium or the endocervical glandular epithelium. "A recent study by Tang, Yang and Sun investigated the mechanism through which EZH2 promotes tumour-associated macrophages in HPV16+ cervical cancer cells." (PMID 41614754, 2025). "This study highlights the therapeutic potential of EZH2 inhibitors—particularly EPZ6438—in HPV-associated cervical cancer cells." (PMID 41614754, 2025). "We report that EZH2 expression is increased in cervical cancer which is associated with hypomethylation of its promoter." (PMID 36172073, 2022). "Our results suggest the participation of EZH2 in the generation of domains with a silencer function in cervical cancer, which regulate the expression of genes associated with cellular senescence." (PMID 36172073, 2022). "Indeed, the current findings of this study hold promise of using EZH2 inhibitors in treating HPV-associated cervical cancers; however, several limitations should be acknowledged." (PMID 41614754, 2025). "Additionally, high EZH2 expression is associated with the repression of the senescent phenotype in cervical cancer patients." (PMID 36172073, 2022). "In addition, the expression of LINC01535 is inversely associated with that of miR‐214 and positively associated with that of EZH2 in cervical cancer tissues, which support the negative regulation of miR‐214/EZH2 loop by LINC01535." (PMID 31273925, 2019). "Moreover, the expression of LINC01535 is reversely associated with the expression of miR‐214 and positively associated with the expression of EZH2 in cervical cancer tissues." (PMID 31273925, 2019). "Moreover, EZH2 has been strongly associated with advanced stage and poor prognosis in squamous cell malignancies including cervical cancer, esophageal squamous cell carcinoma and head and neck cancer." (PMID 27793053, 2016). "Interestingly, cervical carcinoma cells appear addicted to EZH2; depletion caused G1 cell cycle arrest and a low level of apoptosis." (PMID 23673719, 2013). "In summary, our results indicate that the EZH2–PTEN–AKT axis is a key driver of reduced EGFR-TKI sensitivity in radiation-adapted cervical cancer cells." (PMID 41156200, 2025). "Elevated EZH2 expression has been reported across several malignancies, including renal, prostate, and cervical cancers, while its expression remains low or undetectable in normal tissues." (PMID 41614754, 2025). "In particular, EZH2 inhibition was shown to induce reversal of cisplatin resistance and to increase cells’ sensitivity to cisplatin in cervical cancer cells." (PMID 41614754, 2025). "Overall, this study demonstrates the therapeutic effect of EZH2 inhibitors on cervical cancer cells." (PMID 41614754, 2025). "In cervical cancer, EZH2 overexpression drives aggressive phenotypes by epigenetically silencing TIMP2, a key inhibitor of matrix metalloproteinases, through promoter hypermethylation." (PMID 41029427, 2025). "Enhancer of zeste homolog 2 (EZH2), a histone methyltransferase, is frequently overexpressed in HPV-associated cervical cancers and has been linked to tumour progression." (PMID 41614754, 2025). "This mechanistic link positions EZH2 as a master regulator of immune evasion in cervical cancer, highlighting its therapeutic potential when targeted alongside immunotherapies." (PMID 41029427, 2025). "Evidence in the literature also indicates that PVT1 promotes cervical cancer progression by silencing MIR200B through EZH2 interaction, leading to histone H3K27 trimethylation and MIR200B inhibition." (PMID 39372928, 2024). "The suppression of DUSP5 through EZH2-mediated methylation further enhances cervical cancer cell proliferation and migration." (PMID 39090630, 2024).
cervical carcinoma (continued). "A total of 60 consecutive histopathologically confirmed cases of carcinoma cervix from January 2018 to June 2022 were subjected to immunohistochemistry (IHC) for EZH2." (PMID 37131568, 2023). "So far, various mechanisms have been postulated by which EZH2 is involved in cervical cancer progression." (PMID 37131568, 2023). "In the present study, out of 60 cases of carcinoma cervix, high expression of EZH2 was present in 41 cases (68.3%)." (PMID 37131568, 2023). "In the present study, it was observed that the EZH2 had a significant correlation with histologic subtypes of carcinoma cervix (p = 0.018)." (PMID 37131568, 2023). "Immunohistochemical expression of biomarkers such as EZH2 can be utilized as indicators of disease progression, aggressiveness and can predict prognosis in carcinoma cervix." (PMID 37131568, 2023). "Although, most of the drugs targeting EZH2 for cervical cancer are under clinical trial, however, new EZH2 inhibitor drug such as tazemetostat is approved by FDA for treatment for sarcomas." (PMID 37131568, 2023). "In an another mechanism, it is postulated that EZH2 activates the Wnt/β-catenin signaling pathway and enhances the cell proliferation in cervical cancer." (PMID 37131568, 2023). "We demonstrated that miR-138 suppresses tumor progression by targeting EZH2 in cervical cancer and uncovered the role of DNA methylation in the miR-138 promoter in its downregulation." (PMID 35505294, 2022). "The functional and mechanistic studies indicated that miR-138 can suppress cervical cancer cell growth and metastasis by targeting EZH2." (PMID 35505294, 2022). "DNA methylation inhibited miR-138 transcription, and enhancer of zeste homolog 2 (EZH2) downregulation mediated the tumor suppressor function of miR-138 in cervical cancer." (PMID 35505294, 2022). "Another study suggested that LINC01535 enhanced distant metastasis via mediating EZH2-targeted miR-214 in cervical cancer." (PMID 35802620, 2022). "Another lncRNA EBIC which can bind to enhancer of zeste homolog 2 (EZH2) in cervical cancer has been reported to promote cell invasion by repressing E-cadherin." (PMID 33777808, 2021). "They found that pT345-EZH2 and pT487-EZH2 facilitate EZH2 ubiquitination and hence its degradation by the proteasome pathway in human cervical cancer cells." (PMID 33308321, 2020). "LINC01535 was found to be elevated in cervical cancer tissue, is associated with a poor prognosis in cervical cancer and promotes the progression of cervical cancer via miR-214 EZH2." (PMID 33173530, 2020). "We next analysed the correlation between LINC01535 and miR‐214/EZH2 expression in cervical cancer tissues." (PMID 31273925, 2019). "LINC01535 promotes cervical cancer cell growth, migration and invasion in vitro and xenograft growth in vivo via repressing the miR‐214/EZH2 regulatory loop." (PMID 31273925, 2019). "In conclusion, this study reveals that LINC01535 promotes cervical cancer progression via repressing the miR‐214/EZH2 regulatory loop." (PMID 31273925, 2019). "IHC staining of EZH2 displayed that the cervical cancer tissues with strong EZH2 staining intensity had higher LINC01535 expression and lower miR‐214 expression than those of cervical cancer tissues with weak EZH2 staining intensity." (PMID 31273925, 2019). "This lncRNA has been shown to associate with EZH2 and appears to facilitate the silencing of E-cadherin by EZH2 in cervical cancer." (PMID 28430163, 2017). "In cervical cancer cells, overexpression of EZH2 correlates with cell growth, proliferation, and cancer progression suggesting poor patient survival." (PMID 28740569, 2017).
cervical carcinoma (continued). "It has recently been demonstrated that disruption in EZH2 expression reverses the chemotherapy drug resistance in cervical cancer cells partly by increasing the expression of Dicer." (PMID 28740569, 2017). "The use of the EZH2 inhibitor GSK343 on the cervical carcinoma cell lines HeLa and SiHa in vitro was found to reduce cell proliferation, motility and invasiveness." (PMID 27557505, 2016). "We next elucidated the mechanism whereby EZH2 activates the Wnt/β-catenin pathway in cervical cancer." (PMID 27092879, 2016). "Taken together, these results demonstrate that the EZH2-mediated promotion of cervical cancer cell proliferation is regulated by activation of the Wnt/β-catenin pathway." (PMID 27092879, 2016). "The average relative EZH2 expression level was 0.71 in the cervical cancer tissues and 0.04 in the normal cervical tissues." (PMID 27092879, 2016). "The cervical cancer tissues had a 17-fold higher EZH2 expression level than the normal cervical tissues (p<0.01)." (PMID 27092879, 2016). "As a prognostic biomarker of cervical carcinoma, the expression of EZH2 has been previously found to be informative." (PMID 27557505, 2016). "Next, using immunohistochemistry and western blot assay, we found that EZH2 showed different expression levels in five cervical cancer cell lines, including HeLa, SiHa, C33A, CaSki and HT-3." (PMID 27092879, 2016). "Subsequently, to further explore the function of EZH2 in cervical carcinogenesis, cervical cancer cells with exogenous or disrupted EZH2 were obtained in cervical cancer cell lines HeLa and SiHa." (PMID 27092879, 2016). "The results showed that EZH2 significantly promoted tumor growth in vivo and the proliferation of cervical cancer cells in vitro by accelerating the cell cycle transition of cervical cancer cells from G0/G1 phase to S phase." (PMID 27092879, 2016). "Viral E7 activates EZH2 in cervical cancer cells and is believed to contribute to the apoptotic resistance of HPV-transformed cells." (PMID 27793210, 2016). "Variable expression was seen in a number of EBV-transformed LCL, with low expression of EZH2 mRNA in the cervical carcinoma cell line Caski, and in normal fibroblasts." (PMID 17024127, 2006). "Furthermore, EZH2-mediated epigenetic silencing of the CCL22-CCR4 axis in cervical cancer exemplifies its role in promoting metastasis and immune dysregulation." (PMID 41029427, 2025). "This study aimed to investigate the effect of EZH2 inhibitors on cervical cancer cells and evaluate whether their therapeutic effects might be associated with the HPV status in cells." (PMID 41614754, 2025). "Whether EZH2-driven PTEN suppression contributes to therapy failure in the context of radiation-acquired adaptation in cervical cancer remains unclear." (PMID 41156200, 2025). "This study aimed to determine whether EZH2-mediated PTEN silencing drives afatinib resistance via AKT activation in radiation-resistant cervical cancer cells." (PMID 41156200, 2025). "This indicates that EZH2 inhibitors, such as EPZ6438, could be considered as a potential therapeutic drug in managing high-risk HPV-associated cervical cancer due to its tendency to decrease HPV E6 expression." (PMID 41614754, 2025). "The observed EZH2–EMT-associated phenotypes and their underlying mechanisms have important implications for cervical cancer development and severity, which suggests that targeting this pathway through specific inhibitors would result in general epigenetic reprogramming." (PMID 38146588, 2023).
cervical carcinoma (continued). "The possible explanation of increasing EZH2 immunoexpression with ascending stages of cervical cancer might be that the EZH2 induces EMT directly by repressing the expression of E-cadherin through H3K27 trimethylation." (PMID 37131568, 2023). "We further examined whether EZH2 suppression is critical for miR-138–induced proliferation, apoptosis, and invasion in cervical cancer cells." (PMID 35505294, 2022). "Hence, the objective of this study was to determine the role of EZH2 in transcriptional regulation in cervical cancer." (PMID 36172073, 2022). "EBIC may act as an oncogenic lncRNA through cooperation with EZH2 and may promote the migration of cervical cancer cells." (PMID 35262965, 2022). "EZH2 is the direct downstream target gene of miR-137 in cervical cancer." (PMID 33413360, 2021). "For example, recruited EZH2 by long non-coding RNA (lncRNA) LINP1 could contribute to reduced expression of KLF2 in cervical cancer." (PMID 34462420, 2021). "In addition, other transcription factors such as NANOG, OCT4, LGR5, and EZH2 promote tumor formation in cervical cancer." (PMID 33947962, 2021). "RIPK4 can combine with EZH2, which is a polycomb group of genes that regulates epidermal–mesenchymal transformation and angiogenesis via suppressing tumor suppressor genes, to enhance lymph node metastasis in cervical cancer." (PMID 34124253, 2021). "To explore whether the LINC01535/miR‐214/EZH2 regulatory axis exists in clinical tissue specimens, we collected 80 pairs of cervical cancer tissues and matched adjacent normal cervical tissues." (PMID 31273925, 2019). "To determine whether the oncogenic roles of LINC01535 in cervical cancer are dependent on the repression of miR‐214/EZH2 regulatory loop, we stably overexpressed miR‐214 or stably silenced EZH2 in LINC01535 stably overexpressed HeLa cells." (PMID 31273925, 2019). "Moreover, the expression of LINC01535 is negatively correlated with the expression of miR‐214/EZH2 regulatory loop in cervical cancer." (PMID 31273925, 2019). "Furthermore, the critical tumour suppressors miR-200b/a/429 have been reported to be EZH2 target genes in cervical cancer and HCC." (PMID 28487474, 2017). "Furthermore, an analysis of ten biopsies of normal cervical tissue, HPV+ high-grade precancerous lesions, and HPV+ cervical carcinomas detected similarly elevated levels of EZH2 protein in the HPV expressing samples." (PMID 29069809, 2017). "The number of specimens with positive EZH2 staining gradually increased from 12.5% (5/40) in the normal cervical tissues to 43.9% (18/41) in the cervical cancer in situ tissues, and then to 74.2% (46/62) in the cervical cancer tissues." (PMID 27092879, 2016). "Furthermore, we found that EZH2 expression was significantly positively correlated with β-catenin, cyclin D1, and c-myc expression in 24 randomly selected cervical cancer samples." (PMID 27092879, 2016). "Here, we show that EZH2 expression gradually increases during the progression of cervical cancer." (PMID 27092879, 2016). "Additionally, EZH2 down-regulation in cervical cancer cells silenced by shRNA was also observed in HeLa and SiHa cells (Figure 2B1), H3K27me3 levels were also obviously decreased." (PMID 27092879, 2016). "Collectively, these results suggest that EZH2 may accelerate the cell cycle transition at the G1/S phase and further promote the proliferation of cervical cancer cells." (PMID 27092879, 2016). "However, no clinical trials using EZH2 inhibitor treatment on HPV-associated cervical cancer have been reported." (PMID 41614754, 2025). "Moreover, we conducted transfection experiments to downregulate EZH2 expression in SiHa and C33A cells and determine whether EZH2 plays regulatory roles in cervical cancer." (PMID 35505294, 2022).
cervical carcinoma (continued). "Our findings suggest that HPV+ cervical cancer cells display greater resistance to cisplatin compared to HPV-cells, whilst an increased sensitivity to EZH2 inhibitor EPZ6438 was indicated in vitro." (PMID 41614754, 2025). "Considering that EZH2 inhibitors can potentially reverse aberrant DNA patterns, methylation-specific modifications in both HPV- and HPV+ cervical cancer should be analysed to further determine effectiveness of EZH2 inhibitors." (PMID 41614754, 2025). "Catalysation of methylation of Histone 3 (H3) is the main function of EZH2; therefore, the protein expression of epigenetic change was evaluated for EZH2 and H3 in HPV- and HPV+ cervical cancer cells." (PMID 41614754, 2025). "Proliferation assay and flow cytometry results showed that EZH2 inhibitors effectively induced apoptosis and arrested cells in G0/G1 phase in both HPV+ and HPV- cervical cancer cells." (PMID 41614754, 2025). "In the context of cervical cancer, ARAP1-AS1 recruits EZH2 to the DUSP5 promoter, resulting in epigenetic silencing of DUSP5." (PMID 39090630, 2024). "The epigenetic regulation driven by EZH2 plays a crucial role in the expression of CCL22-CCR4 and EMT in CC cells, thereby offering potential therapeutic targets for cervical cancer treatment." (PMID 39513112, 2024). "Within this context, Enhancer of Zeste Homolog 2 (EZH2) mRNA emerges as a histone methyltransferase gene responsible for adding methyl groups to histone proteins and raised in cervical cancer." (PMID 38956668, 2024). "A PPIN of 90 genes identified FLT1, IGF2, IRS1, JUN, KDR, ZEB1, TIMP2 (downregulated), and EZH2, SOX2, and MYB (upregulated) in cervical cancer samples when compared with normal samples." (PMID 36879084, 2023). "In the previous study, ARAP1-AS1 was discovered to recruit EZH2 to regulate the expression of dual specificity phosphatase 5, a downstream gene of ARAP1-AS1, therefore affecting the development of cervical cancer." (PMID 35291911, 2022). "Silence in the expression of EZH2 reversed the effects of KDM6A and KDM6B, confirming the important role of EZH2 during HPV infection and cervical cancer." (PMID 28740569, 2017). "Multiple studies have reported EZH2 upregulation in HPV+ cancer cell lines, with similarly higher expression reported in small studies of HPV+ cervical carcinomas." (PMID 29069809, 2017). "However, the molecular mechanisms of EZH2 in cervical carcinoma are largely unknown." (PMID 27092879, 2016). "Analysis of the IHC scores also revealed that the immunoreactivity score (IRS) of EZH2 staining was 1.5 for the normal cervical tissues, 3.1 for the CIS tissues and 6.6 for the cervical cancer tissues (p<0.05)." (PMID 27092879, 2016). "However, the exact mechanism of EZH2 in the promotion of cervical cancer is largely unknown." (PMID 27092879, 2016). "Our data demonstrate that the expression level of EZH2 was significantly higher in HPV+ vs. HPV- tumors (p = 0.006), consistent with the results reported for HPV+ cervical cancer." (PMID 27793210, 2016).